GSTO1 (glutathione S-transferase omega 1)
Diseases named in the same sentence as GSTO1 in open-access papers (continued):
Sharing a sentence is not in itself a finding about the gene and the disease.
colon cancer (4 papers, 2016 to 2024). "The enzyme glutathione S‐transferase omega class 1 (GSTO1) is known to be involved in cisplatin resistance in colon cancer." (PMID 38750006, 2024). "GSTO1 knock-down by the inhibitor C1-27 in colon cancer cell line HCT116 resulted in down-regulation of Dickkopf-related protein 1 (DKK1), thombospondin 1 (THBSS1) and CAV-1." (PMID 31889941, 2019). "Here the authors identify a small molecule inhibitor of GSTO1 that effectively inhibits tumor growth in colon cancer models, and establish its mechanism of action." (PMID 27703239, 2016). "These potent GSTO1 inhibitors suppress cancer cell growth, enhance the cytotoxic effects of cisplatin and inhibit tumour growth in colon cancer models as single agent." (PMID 27703239, 2016). "In addition, previous studies have reported the involvement of GSTO1 in cisplatin resistance in colon cancer." (PMID 38750006, 2024).
diabetes (4 papers, 2015 to 2023). "What was found when the risk for diabetes or diabetes nephropathy was assessed in our study was that carriers of at least one GSTO1 rs4925 variant allele (*CA+ AA) were less prone to T2DM development." (PMID 36676788, 2023). "Among six investigated GST polymorphisms, a significant association between GST genotype and susceptibility for development of diabetes mellitus was found for the GSTM1, GSTT1, GSTP1 (rs1138272) and GSTO1 (rs4925) polymorphisms." (PMID 36676788, 2023). "On the contrary, individuals with the GSTO1*CA genotype had significantly lower odds of symptomatic diabetes development compared to the carriers of the wild-type GSTO1*CC genotype (OR = 0.28, 95%CI = 0.15–0.51, p < 0.001)." (PMID 36676788, 2023). "Eleven genes in the Glutathione metabolism pathway (Gpx7, Gss, Gsta3, Gstm2, Gstm5, Gstm7, Gsto1, Gstp1, Gstt1, Gstt2 and Mgst2) were observed in type 2 diabetes mellitus." (PMID 25788156, 2015).
esophageal squamous cell carcinoma (4 papers, 2015 to 2023). Esophageal squamous cell carcinoma (ESCC) is a type of esophageal carcinoma (EC) that can affect any part of the esophagus, but is usually located in the upper or middle third. "Finally, gene targets GSTO1 and ALDH2 are associated with breast, ovarian, and esophageal squamous cell cancer." (PMID 26472186, 2015). "GSTO1 has been found to be highly expressed in esophageal squamous cell carcinoma (ESCC) and is believed to play an important role in tumor progression by regulating various cellular processes, including cancer cell proliferation, apoptosis, and migration." (PMID 37047688, 2023).
Insulin resistance (4 papers, 2017 to 2024). Increased resistance towards insulin, that is, diminished effectiveness of insulin in reducing blood glucose levels. "Our observation of diminished IL-1β expression in the serum and spleen of GSTO1-1 deficient mice treated with LPS therefore reveals a possible mechanism by which GSTO1-1 deficiency attenuates insulin resistance in mice on a high fat diet." (PMID 29259211, 2017). "GSTO1-1 deficiency ameliorates the inflammatory response stimulated by LPS and attenuates the inflammatory impact of a high fat diet on glucose tolerance and insulin resistance." (PMID 29259211, 2017). "In a study on mice, the absence of GSTO1 was found to enhance the inflammatory response triggered by LPS while mitigating the inflammatory effects of a high-fat diet on glucose tolerance and insulin resistance." (PMID 39000259, 2024).
lung carcinoma (4 papers, 2019 to 2025). "The increased levels of GSTO1 and PRDX6 in plasma of lung cancer patients may reflect their protective role in the cancer redox environment, or may be associated with the activation of antioxidant pathways resulting from cigarette smoking." (PMID 32575471, 2020). "Glutathione S-Transferase Omega 1 (GSTO1), Sulfotransferase Family 2B Member 1 (SULT2B1), ADH1A, ADH1B, and ADH1C were downregulated in lung cancer versus normal tissue, while ALDH3A2 and MTHFD2 were upregulated in lung cancer tissue versus normal adjacent tissue." (PMID 31717324, 2019).
chronic obstructive pulmonary disease (3 papers, 2022 to 2024). A chronic and progressive lung disorder characterized by the loss of elasticity of the bronchial tree and the air sacs, destruction of the air sacs wall, thickening of the bronchial wall, and mucous accumulation in the bronchial tree. "Studies on patients with chronic obstructive pulmonary disease (COPD) showed that extracellular GSTO1-1 may modulate glutathione (GSH) homeostasis and antioxidant defense in airway secretions." (PMID 35330457, 2022).
COVID-19 (3 papers, 2022 to 2025). A disease caused by infection with severe acute respiratory syndrome coronavirus 2. "Conversely, Djukic reported a statistically significant increase in the risk of developing COVID-19 in individuals with specific GSTO polymorphisms, including the GSTO1 AA, GSTO2 AG, and GSTO2 GG genotypes." (PMID 40867811, 2025). "Haplotype analysis confirmed a high degree of linkage disequilibrium between GSTO1 and GSTO2 polymorphisms, and the cumulative presence of risk genotypes further increased the probability of developing COVID-19." (PMID 40867811, 2025). "Variants such as SOD2 rs4880, GSTP1, GSTO1, PON1, and NOS3 have been associated with reduced enzymatic activity, impaired detoxification of ROS, and worsened COVID-19 severity or post-acute sequelae." (PMID 41209585, 2025). "Indeed, we found that the polymorphisms in GSTP1, GSTM3, GSTO1 and GSTO2 genes were associated with significant odds of COVID-19 development, while the combined GSTP1 and GSTM3 genotype even exhibited cumulative risk regarding both COVID-19 occurrence and COVID-19 severity." (PMID 35624818, 2022).
Hypertension (3 papers, 2015 to 2025). The presence of chronic increased pressure in the systemic arterial system. "As MASLD and hypertension are common co-morbidities, a study regarding differences in GSTM1 and GSTO1 protein expression in normotensive and hypertensive rats was performed which showed significant GSTO1 downregulation and no change in GSTM1 levels in hypertensive rats." (PMID 39443317, 2025).
ovarian carcinoma (3 papers, 2019 to 2025). A malignant neoplasm originating from the surface ovarian epithelium. "More recently, a study of Serbian subjects confirmed that homozygous carriers of the GSTO2*N142D variant have an increased risk of ovarian cancer, whereas carriers of the H4 haplotype (i.e., GSTO1*A variant allele and GSTO2*A wild-type allele) have a lower OC risk." (PMID 40724836, 2025). "The GSTO1 upregulation has been reported in different cancers, including bladder, pancreatic, ovarian cancer and esophageal adenocarcinoma." (PMID 31861116, 2019). "The overexpression of GSTO1-1 has been also reported in esophageal squamous cell carcinoma, pancreatic cancer, and ovarian cancer." (PMID 31861116, 2019). "However, although both GSTO1 and GSTO2 variant genotypes seem to increase the probability of developing OC, statistical analysis indicated the GSTO2*G allele as the ovarian-cancer-risk-associated one." (PMID 38732205, 2024).
prostate carcinoma (3 papers, 2021 to 2025). A carcinoma that arises from epithelial cells of the prostate gland. "Gene polymorphisms of GSTM1, GSTT1, GSTO1 rs4925, GSTO2 rs156697, GSTP1 rs1695, and GSTP1 rs1138272 and risk of overall mortality in prostate cancer patients by Cox proportional hazards regression models." (PMID 33937322, 2021). "Haplotypes of GSTO1 rs4925 and GSTO2 rs156697 in relation to the risk of prostate cancer." (PMID 33937322, 2021). "Considering the pleiotropic roles of glutathione transferase (GST) omega class members in redox homeostasis, we hypothesized that polymorphisms in GSTO1 and GSTO2 might contribute to prostate cancer (PC) development and progression." (PMID 33937322, 2021). "MR-PRESSO analyses showed no horizontal multiplicity in causality for prostate cancer for both GSTP and GSTO1 (global test, p = 0.307 and p = 0.347), and neither had outliers." (PMID 40426879, 2025).
urothelial carcinoma (3 papers, 2011 to 2025). A malignant neoplasm derived from the transitional epithelium of the urinary tract (urinary bladder, ureter, urethra, or renal pelvis). "On the other hand, the analysis of the haplotypes/diplotypes of GSTO1 and GSTO2 revealed that the diplotype combining GSTO1*C419/GSTO2*A183/GSTO2*G424 had a significantly higher risk of urothelial carcinoma, as compared with other diplotypes." (PMID 40724836, 2025).
acute lymphoblastic leukemia (2 papers, 2018 to 2024). Leukemia with an acute onset, characterized by the presence of lymphoblasts in the bone marrow and the peripheral blood. "So far, an association between the GSTO1*C419A polymorphism (rs4925) and susceptibility to various cancers, including acute lymphoblastic leukemia, hepatocellular, breast, bile duct, non-small cell lung, colon, and testicular cancer has been confirmed." (PMID 38732205, 2024).
asthma (2 papers, 2022 to 2024). "However, despite extensive research, a limited number of studies have successfully established a definitive association between GSTO1 and asthma." (PMID 38730525, 2024). "Several asthma-related genes were identified: detoxification enzymes (Cyp2a5, Gsto1, Gstp1, Gstm1, and Aldh1a1) were downregulated while Hmgb1 (alarmin) was upregulated." (PMID 35627266, 2022). "Glutathione S‐transferase omega‐1 (GSTO1), leukocyte immunoglobulin‐like receptor subfamily B member 4 (LIRB4), and placental growth factor (PIGF) were associated with a greater risk of childhood asthma." (PMID 38730525, 2024).
atherosclerosis (2 papers, 2021 to 2022). A disease characterized by the build-up of fatty material and calcium deposition in the arterial wall resulting in partial or complete occlusion of the arterial lumen. "Gsto1, which presumably modulates the severity and expansion of atherosclerosis, was weakly expressed in SMC_1 in the HFD group." (PMID 34548614, 2021).
bladder tumor (2 papers, 2015 to 2024). "Our results showed that patients with the GSTO1 CC genotype had a significantly abridged risk of bladder tumor recurrence (CC/(AC+AA): HR = 0.51, 95% CI = 0.27–0.95) after treatment with epirubicin, which was in agreement with the results of these studies." (PMID 26354850, 2015). "Collectively, the in vivo animal assay supported our findings that GSTO1 enhanced cisplatin resistance through the promotion of cisplatin efflux from bladder tumor tissue." (PMID 38750006, 2024).
cervical cancer (2 papers, 2018 to 2025). A primary or metastatic malignant neoplasm involving the cervix. "It would appear that GSTO1 A140D SNPs likely play a role in the level of susceptibility to HPV-related cervical cancer." (PMID 30115608, 2018). "Therefore, we suggest that GSTO1 A140D gene polymorphisms likely play an inconspicuous role in the level of susceptibility to HPV-related cervical cancer." (PMID 30115608, 2018). "This study investigated the association between GSTO1 A140D and GSTO2 N142D polymorphisms and susceptibility to HPV infection and cervical cancer progression in Iranian women." (PMID 30115608, 2018). "We found a significant association between the GSTO1 A140D gene polymorphism and HPV 6, 16, 18, 16/18 infections and cervical cancer in Iranian women." (PMID 30115608, 2018). "Only one study focused on GSTO1-1 and GSTO2-2 in cervical cancer in Iranian women." (PMID 40724836, 2025).
Clear Cell Renal Cell Carcinoma (2 papers, 2019 to 2021). "Our results showed that homozygous carriers of GSTO1*A/A variant genotypes are at increased risk of PC, which is in agreement with another urological cancer, clear cell renal cell carcinoma." (PMID 33937322, 2021). "We investigated the the prognostic significance of GSTO1 (rs4925) and GSTO2 (rs156697 and rs2297235) polymorphisms in clear cell renal cell carcinoma (ccRCC) patients." (PMID 31861116, 2019).
cystic fibrosis (2 papers, 2022 to 2024). Autosomal recessive disorder caused by pathogenic variants in the CFTR gene (cystic fibrosis transmembrane conductance regulator), which encodes a chloride and bicarbonate channel expressed in epithelial cells, and follow the diagnosis criteria. "Another independent study further established a correlation between GSTO1 and the severity of inflammation and respiratory dysfunction in patients with cystic fibrosis." (PMID 38730525, 2024).
dementia (2 papers, 2016 to 2024). Loss of intellectual abilities interfering with an individual's social and occupational functions. "We performed an MDR analysis as well as a bioinformatic analysis to identify interactions between the genes GSTO1_rs4925, AGER_rs2070600, and ESR1_rs3844508 associated with susceptibility to dementia." (PMID 39596595, 2024). "We observed associations between the polymorphism of GSTO1 and risk of dementia for the site rs4925 with the recessive model (OR = 1.720, 95% CI = 1.166–2.537 p = 0.006)." (PMID 39596595, 2024). "Our results show that the GSTO1_rs4925 and AGER_rs2070600 gene loci are associated with CC susceptibility to dementia." (PMID 39596595, 2024). "Our results showed that GSTO1_rs4925 was associated with the risk of developing dementia when the genotype AA was present, while the presence of the C allele seemed to show protection against the development of dementia." (PMID 39596595, 2024). "Among the 2384 unique gene correlates of Gsto1 expression in hippocampus are 128 genes that share a high co-incidence of literature citations—24 of which are known to be associated with AD or dementia, including well studied candidates Chmp2b, Optn, Dlst, Sod2, and Acat1." (PMID 26829228, 2016).
fetal growth restriction (2 papers, 2016 to 2023). A fetus that does not grow beyond the 10th percentile of conventionally accepted weight for gestational age. "The GSTO1 gene, which encodes an arsenic detoxification enzyme, glutathione S-transferase omega 1, is the only gene in this list to have a prior association with fetal growth restriction." (PMID 27330572, 2016). "Also, the level of GSTO1 is related to fetal intrauterine growth restriction." (PMID 37803047, 2023).
hepatic cancer (2 papers, 2016 to 2021). "GSTO1 Glutathione S-transferase omega-1 polymorphisms are associated with the increased risk of developing breast and liver cancer and have very recently been implicated in squamous cell, colorectal, and melanoma as a modulator of cell growth and immune response." (PMID 34589115, 2021).
Hypoglycemia (2 papers, 2011 to 2016). A decreased concentration of glucose in the blood. "We have previously shown by qPCR, the increase of Gpx3 (the top gene up-regulated by hypoglycemia; fold change = 4.8), and Gsto-1 (up-regulated by hypoglycemia; fold change = 1.9) in comparison with euglycemic control situation." (PMID 26918849, 2016). "Analysis of retinal explants showed that in vitro exposure to low glucose (2 mM) for a 48-h period significantly increased the expression of Gpx3 and Gsto1 to the same extent as in vivo hypoglycemia." (PMID 21738719, 2011). "In mouse, hypoglycemia induced up-regulation of Gpx3 and Gsto1, which may partially explain the 40% decrease of retinal GSH scavenger seen in our experiments." (PMID 21738719, 2011). "We also observed that both Gpx3 and Gsto1 enzymes, which were up-regulated during a single hypoglycemic clamp, were indeed down-regulated (Gpx3) or not changed (Gsto1) during recurrent hypoglycemia." (PMID 26918849, 2016).
inflammatory bowel disease (2 papers, 2017 to 2023). A spectrum of small and large bowel inflammatory diseases of unknown etiology. "Paradoxically, GSTO1-1-deficient mice exhibited a more severe inflammatory response and increased bacterial escape in a model of inflammatory bowel disease." (PMID 38012707, 2023). "In contrast, GSTO1-1 deficient mice show a more severe inflammatory response and increased escape of bacteria from the colon into the lymphatic system in a dextran sodium sulfate mediated model of inflammatory bowel disease." (PMID 29259211, 2017).
lymphoma (2 papers, 2014 to 2016). A malignant (clonal) proliferation of B- lymphocytes or T- lymphocytes which involves the lymph nodes, bone marrow and/or extranodal sites. "GSTO1 was significantly overexpressed in colorectal, head and neck, breast and oesophageal cancers, as well as in melanomas and lymphomas." (PMID 27703239, 2016). "Mouse GSTO1 was indeed identified because of its overexpression in a mouse lymphoma cell line presenting with resistance against a variety of chemo-therapeutics." (PMID 24690901, 2014).
Myalgia (2 papers, 2022 to 2025). "On the other hand, the presence of GSTP1 Ile and GSTO1 Ala alleles exhibited cumulative risk regarding long-COVID myalgia in carriers of combined GPX1LeuLeu/GPX3CC genotype." (PMID 35624818, 2022). "In this study, apart from the GSTP1 Val allele, the GSTO1 Asp allele also exhibits a modifying effect on the probability of the occurrence of myalgia in long-COVID patients, which is even more potentiated in individuals carrying both of these alleles." (PMID 35624818, 2022). "Indeed, individuals carrying GSTP1 Val or GSTO1 Asp allele exhibited lower odds of long-COVID myalgia development, both independently and in combination." (PMID 35624818, 2022). "Indeed, the data obtained showed that individuals carrying GSTP1 Val or GSTO1 Asp allele exhibit lower odds of long-COVID myalgia development, which was even more potentiated in individuals carrying both of these alleles." (PMID 35624818, 2022). "Furthermore, the combined presence of GSTP1 Ile and GSTO1 Ala alleles exhibited cumulative risk regarding long-COVID myalgia in carriers of the combined GPX1 LeuLeu/GPX3 CC genotype." (PMID 35624818, 2022). "The combined effect of risk genotypes (GSTP1 AB IleIle, GSTO1 AlaAla, GPX1 LeuLeu, and GPX3 CC) markedly increased the probability of myalgia, suggesting a cumulative genetic burden." (PMID 40867811, 2025). "What is more, in individuals carrying combined GSTP1ABValVal/GSTO1 AspAsp genotype, the odds of having myalgia were even lower (OR = 0.24, 95%CI 0.09–0.66) when compared to carriers of combined GSTP1IleIle/GSTO1AlaAla genotype." (PMID 35624818, 2022).
neuroblastoma (2 papers, 2021 to 2022). Neuroblastoma (NB) is the most common solid, extracranial childhood tumor. "For example, GSTO1-1 interacts with AKT and MEK1/2, activating AKT signaling in human neuroblastoma cells." (PMID 35936694, 2022). "Using the GSTO1-specific inhibitor, ML175, they showed that GSTO1 enzyme activity inhibits the activation of these kinases and indirectly regulates the survival, growth, and metabolism of neuroblastoma cells." (PMID 33946704, 2021).
pancreatic cancer (2 papers, 2016 to 2023). "After Bmi1 knockdown, the expression of antioxidant genes including CAT, MnSOD, GSTO1, NQO1 and SOD decreased significantly in pancreatic cancer cells." (PMID 27177084, 2016).
Stroke (2 papers, 2009 to 2015). Sudden impairment of blood flow to a part of the brain due to occlusion or rupture of an artery to the brain. "The C419A (NCBI SNP cluster ID, rs 4925) polymorphism in GSTO-1 gene has been reported to be involved in stroke." (PMID 19624857, 2009). "We hypothesized that the MTHFR C677T and GSTO-1 C419A polymorphisms may modify the response of the brain to cerebral ischemia and ultimately impact the final stroke volume." (PMID 19624857, 2009). "Other SNPs in genes involved in inflammation (APOE and IL6), oxidative stress (NOS3 and SOD2), and As metabolism (AS3MT, CBS, GSTO1, and MTHFR) showed nominally significant interactions with well-water As for associations with CVD, CHD, or stroke." (PMID 25575156, 2015). "There was no significant influence of the MTHFR (p = 0.72) or GSTO-1 (p = 0.58) polymorphisms on the stroke volume." (PMID 19624857, 2009).
transitional cell carcinoma (2 papers, 2018 to 2023). A malignant neoplasm arising from the transitional epithelium, usually affecting the urinary bladder, ureter, or renal pelvis. "In transitional cell carcinoma, GSTO1 co-immunoprecipitated with GSTP1, Akt and ASK1." (PMID 30487385, 2018).